FXR1 (FMR1 autosomal homolog 1)
Diseases named in the same sentence as FXR1 in open-access papers (continued):
Sharing a sentence is not in itself a finding about the gene and the disease.
cancer (continued). "Our pan-cancer analysis revealed a significant upsurge in FXR1 expression across 25 cancer types, including BRCA, CESE, and DLBC." (PMID 38050239, 2023). "We conducted an analysis of FXR1 expression across 33 different cancers, categorizing them into both immune and molecular subtypes." (PMID 38050239, 2023). "Lastly, extensive clinical sample data collection and analysis is necessary to fully utilize FXR1 as a predictive biomarker for different cancers." (PMID 38050239, 2023). "A significant difference in FXR1 expression was observed across molecular and immune subtypes and across types of cancer." (PMID 38050239, 2023). "this study conducted through The Cancer Genome Atlas (TCGA), GTEx, cBioPortal, TISIDB, GEPIA2 and HPA databases to investigated FXR1’s role in cancers." (PMID 38050239, 2023). "The upregulation of FXR1 across most cancer types suggests that FXR1 exerts conserved or fundamental roles in oncogenesis." (PMID 35194031, 2022). "Oncomine cancer data provide evidence for Fxr1-Fbxo4 inhibitory engagement due to Fxr1 overexpression in ESCC at the mRNA level and gain of copy number." (PMID 36329064, 2022). "In summary, combined detection of CCL18 and CXCL1 chemokines, and C1D, TM4SF1, FXR1, and ZNF573 autoantibodies can improve the specificity and sensitivity of OC diagnosis, and its diagnostic efficiency is higher than that of other malignant tumors." (PMID 34995016, 2022). "FXR1 overexpression is regarded as a candidate biomarker predictive of poor survival in multiple solid tumors including NSCLCs and 18 types of human cancers, such as lung, cervix, head, breast, ovarian, and neck squamous carcinoma." (PMID 34291416, 2022). "Previous studies showed that overexpressed FXR1 promoted cancer cell aggressiveness by binding to and disrupting p21 mRNA." (PMID 34946859, 2021). "All but two of these RBPs (FXR1 and PUM1) are splicing factor genes and U2AF1 exhibited significant driver mutation patterns across a wide variety of cancer types." (PMID 32532357, 2020). "FXR1 targets tumor suppressor genes, including p21, to promote the growth and proliferation of cancer cells." (PMID 31940341, 2020). "Blastemal persistence after neoadjuvant therapy has been shown to be a poor prognostic feature, and indeed FXR1 has aligned with worse outcomes in several adult cancers." (PMID 33344257, 2020). "The reduction in miR301a-3p stability upon FXR1 knockdown argues that FXR1 stabilizes miR301a-3p in cancer cells." (PMID 31940341, 2020). "In multiple cancer cell lines, the growth rate was recovered to a level comparable to that of the control, indicating that FXR1 inhibition was responsible for the growth phenotype." (PMID 28767039, 2017). "Our study shows that the tandem Tudor in FXR1 binds to methylated lysine in histone H3 in a similar manner as that in FMR1 and it is required for FXR1’s function in regulating cancer cell proliferation." (PMID 28767039, 2017).
cancer (continued). "The observation that FXR1 knockout mice die shortly after birth and knockdown of FXR1 causes abnormalities in striated muscle and heart in zebrafish raise potential safety concerns with regard to inhibiting FXR1 in cancer patients." (PMID 28767039, 2017). "Summary of FXR1-knockdown-induced anti-proliferation in cancer cell lines and CRISPR-Cas9-engineered cell clones." (PMID 28767039, 2017). "Additional work is needed to warrant the recruitment of TERC by FXR1 and how this process controls telomere length in cancer." (PMID 27606879, 2016). "Of the close to 250 genes located at the 3q26-29 amplicon, we find that ACTL6A and FXR1 are among the 10 and 30 most frequently overexpressed genes in this cancer type, respectively." (PMID 25484917, 2014). "Additionally, the overexpression of FXR1 is a strong indicator of a poor outcome in several types of cancer." (PMID 40149453, 2025). "Furthermore, our data indicate that arginine methylation occurs explicitly in the NES and RGG box domains of FXR1 in cancer cells." (PMID 38709899, 2024). "Hence, in this research, we investigated the effect of arginine methylation on FXR1’s RNA binding capacity including its specificity towards guanine rich regions in cancer cells." (PMID 38709899, 2024). "Both myoblast proliferation and cancer quiescence are regulated by p21 through FXR1." (PMID 38238286, 2024). "Furthermore, loss-of-function of PRMT5 inhibited FXR1 methylation both in vivo and in vitro, affecting FXR1 protein stability, inhibiting RNA-binding activity and cancer cell growth and proliferation." (PMID 38709899, 2024). "FXR1 is upregulated in numerous malignancies, suggesting it is involved in cancer development." (PMID 38238286, 2024). "FXR1 is the key molecule that regulates the progression of cancer." (PMID 38238286, 2024). "However, the enzyme responsible for FXR1’s methylation and how methylated FXR1 impacts RNA binding and alters their expression in cancer cells are unclear." (PMID 38709899, 2024). "This review might help to accelerate the expansion of FXR1 research and therapeutic applications in cancer clinics." (PMID 38238286, 2024).
cancer (continued). "In addition, these models will help in the identification of altered signaling combined through FXR1 in cancer and assist in identifying altered signaling pathways and PTMs that regulate FXR1." (PMID 38238286, 2024). "The findings indicate that the molecular basis for overexpressed FXR1 levels in cancer cells is possibly due to PTM, which could influence its oncogenic function." (PMID 38709899, 2024). "According to the information in hand, FXR1 primarily affects the occurrence of cancer following a major carcinogenic activity by influencing many cancer-related downstream targets, thereby enhancing the biological implication of the initial transforming hit(s) via a “ripple effect”." (PMID 38238286, 2024). "A lot of outstanding research leaves little question regarding the role of FXR1 in cancer etiology." (PMID 38238286, 2024). "Therefore, further research is required to fully comprehend FXR1’s involvement in mRNA synthesis and turnover in cancer cells, leading to cancer growth and proliferation." (PMID 38709899, 2024). "However, further study is required to unravel the molecular mechanism by which FXR1 regulates each of its mRNA targets to promote cancer growth." (PMID 38709899, 2024). "However, the molecular mechanisms and biological effects of FXR1 regulation in cancer have yet to be understood." (PMID 38238286, 2024). "Others have verified that FXR1 depletion using CRISPR-Cas9 is beneficial in cancer treatment." (PMID 38238286, 2024). "FXR1 is an oncogene because it targets and stabilizes many cancer-related mRNAs, and its dysregulation in oncogenesis has a complicated molecular mechanism that varies depending on the cancer type." (PMID 38238286, 2024). "Numerous studies have repeatedly emphasized that FXR1 could be a useful biomarker for predicting the prognosis and treatment response of cancer patients." (PMID 38238286, 2024). "FXR1 is highly expressed in many cancers, including SCC of the lung and HNSCC." (PMID 38238286, 2024). "It is necessary to conduct additional research to investigate how the FXR1-miR301a-3p axis regulates the mRNA stability of other genes, which may drive cancer progression." (PMID 38238286, 2024). "This investigation encompassed a comprehensive analysis of FXR1 across a spectrum of cancer subtypes, uncovering significant correlations between FXR1 expression and clinical prognostic outcomes, mutational profiles, and the presence of immune cell infiltrations." (PMID 38050239, 2023). "This new finding could enhance our comprehension of FXR1’s involvement in cancer immunomodulation and its potential implications for immunotherapy." (PMID 38050239, 2023). "Further clinical validation and exploration of FXR1 in cancer treatment is necessary." (PMID 38050239, 2023). "Additionally, FXR1 showed a correlation with genetic markers of immunomodulators in different cancer types." (PMID 38050239, 2023). "Additionally, we discovered previously unreported mechanisms and pathways through which FXR1 influences cancer progression." (PMID 38050239, 2023). "FXR1 expression exhibited variability within distinct cancer subtypes." (PMID 38050239, 2023). "FXR1 is necessary for cancer cell viability and is sufficient to drive tumorigenesis." (PMID 35194031, 2022). "To determine whether upregulation of FXR1 frequently occurs in other solid tumors, we analyzed the mRNA expression of FXR1 from TCGA across 28 cancer types by paired t-test." (PMID 35194031, 2022). "Fragile X-related gene 1 (FXR1) was identified as a novel cancer driver gene in UCB." (PMID 35194031, 2022). "Together, these results suggest that the upregulation of FXR1 can contribute to cancer development." (PMID 35194031, 2022). "FXR1 was a new driver in the 3q26-29 amplicon and predicted poor prognosis in human cancers." (PMID 35087827, 2021).
cancer (continued). "It will be beneficial to streamline further how the FXR1-miR301a-3p axis targets other genes to regulate their RNA stability, which may affect cancer progression." (PMID 31940341, 2020). "Our analysis of the HNSCC TCGA database revealed that both miR301a-3p and FXR1 are significantly over-expressed in tumor samples, signifying that the association between FXR1 and miR301a-3p may play a role in HNSCC cancer progression." (PMID 31940341, 2020). "The data suggest that FXR1 controls the mature miR301a-3p level in these cancer cells." (PMID 31940341, 2020). "Interestingly, we found four genes (FXR1, RAD50, SP100, SMC6) mutated in 50% of the G1 LS-cancer samples, with the latter three belonging to the APB branch of the ALT-TMM pathway." (PMID 31750255, 2019). "(G) Tumor growth in cancer cell xenograft upon FXR1 knockdown." (PMID 28767039, 2017). "Fxr1 was chosen for further investigation due to its cancer relevance." (PMID 29142209, 2017). "Taken together it suggests that the overexpression of FXR1 protein in cancer may aid in an important mechanism for evasion of cellular senescence through reduced mRNA and protein levels of p21." (PMID 27606879, 2016). "In addition, FXR1 associates and stabilizes non-coding RNA TERC resulting in suppression of cellular senescence and increased cancer growth." (PMID 27606879, 2016). "However, little is known regarding the function of FXR2 in cancer compared to FXR1 and FMRP." (PMID 40149453, 2025). "The preferred amino acids are highly conserved between humans and mice and moderately conserved in a known FXR family member, FMRP, suggesting that these conserved amino acids may play a role in the biological function of FXR1 in cancer cells by contributing to its stability." (PMID 38709899, 2024). "Thus, the current results indicate a straightforward function of FXR1 in cancer cells that may pave the way for targeting the NES/RGG box for therapeutic intervention to elucidate the regulation of tumor suppressors in cancer cells." (PMID 38709899, 2024). "Hence, we determined whether specific arginine methylation carried out by protein methyltransferases targets FXR1 and promotes its stability in cancer cells." (PMID 38709899, 2024). "In addition, we wished to test whether silencing the activity of PRMT5 alters the localization of FXR1 in cancer cells." (PMID 38709899, 2024).
cancer (continued). "Members of the fragile X protein (FXP) family (FMR1, FXR1 and FXR2) are differentially expressed in most types of cancer and major neurodegenerative diseases." (PMID 41117937, 2025). "Based on the effect that PRMT5 had on FXR1 levels, we wanted to see if inhibiting PRMT5 demethylated FXR1 and regulated its actions in cancer cells." (PMID 38709899, 2024). "When FXR1 is depleted, the expression level of proteins BAX, p21, p27, FAK1, DUSP4, and PAI1 increases while BCL2 decreases, all of which are involved in cancer cell death pathways." (PMID 38238286, 2024). "Hence, FXR1 may be a promising target for cMYC reduction in ovarian and other cancers." (PMID 38238286, 2024). "FXR1 is a constituent of stress granules, colocalizes with G3BP1, and has been reported to be overexpressed in cancer." (PMID 37196085, 2023). "We identified that Fragile X-related gene 1 (FXR1), a potential cancer driver gene, is frequently upregulated in UCB and other cancer types." (PMID 35194031, 2022). "Loss of Fbxo4 directly contributes to Fxr1 overexpression in both normal and cancer cells; likewise, re-introduction of Fbxo4 into HNSCC cells triggers Fxr1-dependent senescence, demonstrating the importance of this regulatory loop." (PMID 29142209, 2017). "Our proposed model demonstrates that overexpression of FXR1 post-transcriptionally facilitates p21 mRNA destabilization and reduces its expression in HNSCC, possibly promoting cancer cell proliferation." (PMID 27606879, 2016). "In comparison to FXR1 and FMRP, the role of FXR2 in cancer remains largely unexplored." (PMID 40149453, 2025). "Finally, the enhanced crosslinking and immunoprecipitation (eCLIP) analyses reveal that FXR1 binds with the G4-enriched mRNA targets such as AHNAK, MAP1B, AHNAK2, HUWE1, DYNC1H1 and UBR4 and controls its mRNA expression in cancer cells." (PMID 38709899, 2024). "Nevertheless, our eCLIP data clearly demonstrate that FXR1 interacts with and regulates the target mRNAs both in a positive and negative manner in cancer cells." (PMID 38709899, 2024). "Our published findings indicate that FXR1 helps cancer cells bypass cellular senescence by stabilizing the non-coding telomerase RNA component (TERC) and destabilizing CDKN1A (p21) to promote cell growth." (PMID 38709899, 2024). "CRISPR-Cas9 suppresses the FXR1 gene expression (U2OSFFF and delACAG) in several cancers." (PMID 38238286, 2024). "Deleting the G4-region of p21 mRNA specifically did not interact with FXR1 in cancer cells, indicating that FXR1 prefers G4-sequences in the 3′UTR to regulate the expression of target genes." (PMID 38709899, 2024). "As most RBPs undergo post-translational modifications (PTM) such as phosphorylation, acetylation, methylation, and sumoylation to regulate gene expression in cancer cells, here, we set out to study the impact of PTM on FXR1 and its regulatory effects on its RNA targets." (PMID 38709899, 2024). "Moreover, we have also demonstrated that FXR1 demethylation through inhibition of PRMT5 affected the protein stability and reduced the cancer cell proliferation." (PMID 38709899, 2024).